MIR515-1 (microRNA 515-1)
Synonyms: hsa-mir-515-1; MIRN515-1
Gene: MicroRNA gene on chromosome 19 (53,679,003 to 53,679,085, forward strand). Ensembl gene ENSG00000207616.
Gene Ontology:
Biological process: miRNA-mediated post-transcriptional gene silencing
Homologues: Orthologues: chimpanzee ptr-mir-515-1 (100% identical). Paralogues in human: MIR515-2 (100% identical), MIR518D (81% identical), MIR520C (81% identical), MIR519A2 (80% identical), MIR520E (80% identical), MIR518C (78% identical), MIR516A1 (76% identical), MIR517A (76% identical), MIR524 (76% identical), MIR516A2 (75% identical), MIR519C (75% identical), MIR520F (75% identical), and 12 more.
Diseases named in the same sentence as MIR515-1 in open-access papers:
MIR515-1 is named in the same sentence as 1 disease in open-access papers, as found by Europe PMC text mining. Sharing a sentence is not in itself a finding about the gene and the disease. The quoted sentences say what the papers report.
tumours (1 paper, 2024). "We identified MIR182, MIR183, MIR371, MIR373, MIR512-1, MIR512-2, MIR515-1, and MIR520e exhibiting high expression and MIR216b, MIR887, MIR9-2, and MIR9-3 exhibiting low expression in NANOG H/L tumours." (PMID 38693576, 2024).